FGFR3 (fibroblast growth factor receptor 3)
Diseases named in the same sentence as FGFR3 in open-access papers (continued):
Sharing a sentence is not in itself a finding about the gene and the disease.
tumor (continued). "The mutation analysis revealed that the majority of our tumours (n = 54) had at least one mutation, which was associated with non-invasive growth pattern, whereas only 27/85 tumours had FGFR3 wild type (correlated with more invasive growth, p = 0.059)." (PMID 24650297, 2014). "Several reports also define a role for TAK1 and TAK1-NFκB signaling in the promotion of tumor cell adhesion, and FGFR3 mutations have been reported to decrease cellular attachment to extracellular matrix components in benign tumors." (PMID 24466111, 2014). "When BTC cells overexpressing FGFR3-IIIc were xenografted in immune deficient mice, tumor progression was strongly inhibited as compared to control cells." (PMID 23902722, 2013). "A multicentre study comprising 230 superficial tumours suggested that adding FGFR3 mutation status and Ki-67 positivity to current histopathological criteria improved prediction of progression in about 7% of patients." (PMID 22899908, 2012). "Urine-based tests detecting common FGFR3 mutations are also under development for surveillance of low-grade and -stage tumours and for general population screening." (PMID 22899908, 2012). "We recently showed that most (80%) muscle-invasive tumours with FGFR3 mutations harbour homozygous CDKN2A deletions, resulting in the loss of both P16INk4A and P14ARF." (PMID 23272046, 2012). "We used the statistical SAM test to compare the expression of the selected genes in the tumor group of the same stage but of opposite FGFR3 mutation status (right column)." (PMID 22724020, 2012). "In contrast, in a subsequent larger study of 764 superficial tumours FGFR3 mutation was predictive of a higher rate of recurrence in TaG1 but not TaG3 or T1 tumours." (PMID 22899908, 2012). "The FGFR3-mutated tumor pathway comprised the TaG1 and TaG2 FGFR3-mutated tumors, the T1 FGFR3-mutated tumors and the muscle-invasive FGFR3-mutated tumors (T2–4 tumors)." (PMID 22724020, 2012). "Inverse correlation between FGFR3 mutation and progression in pT1 tumours was also confirmed in a subsequent investigation." (PMID 22899908, 2012). "In patients with a wild-type primary tumor, recurrences were mostly wild-type (49/54 recurrences), while 5 harbored an FGFR3 mutation." (PMID 21072204, 2010). "In spite of this, one patient showed different FGFR3 mutations in the initial and the recurring tumor." (PMID 18590527, 2008). "Mutations of FGFR3 are strongly associated with a low tumour grade and stage, with up to 60–70% of low-grade pTa tumours showing these mutations." (PMID 17579624, 2007).
tumor (continued). "Compared to patients with wildtype FGFR3 tumor, patients with S249C FGFR3 mutated tumors were older (mean age 64 vs. 49.4 years, P = 0.02), and were more likely to be associated with a non-16/18 HPV type in their tumor." (PMID 15869706, 2005). "The current study showed a strong correlation of FGFR3 mutations with tumour grades." (PMID 41375830, 2025). "Since somatic mutations in the TERT promoter and FGFR3 have been found in normal urothelium and are commonly reported in tumor tissues by The Cancer Genome Atlas (TCGA), they are considered potential driver mutations in the development of both low-grade and high-grade NMIBC." (PMID 40995307, 2025). "Both high- and low-grade tumours harboured pathogenic FGFR3 S249C or R248C mutations." (PMID 41375830, 2025). "Furthermore, the percentages of positive FGFR2 and FGFR3 tumor cells were negatively associated with the degrees of tumor differentiation." (PMID 41467942, 2025). "Studies have shown that FGFR3 mutations correlate with lower tumor grades and stages, suggesting that patients with these mutations may benefit more from targeted therapies." (PMID 39761856, 2025). "Particularly in the context of tumor recurrence, FGFR3 mutations may be strongly associated with a high-risk of recurrence in stage Ta tumors." (PMID 38592174, 2024). "It has also been suggested that this loss of FGFR3 mutation during tumor progression may potentially alleviate oncogene-induced upregulation of p16 and related cell cycle checkpoint genes allowing tumor progression." (PMID 39031286, 2024). "While the gene expression changes could emanate from tumor cells themselves, it is also possible that FGFR3 activation may induce a more T cell–inflamed tumor microenvironment than Pten loss in the UPPL model." (PMID 38226620, 2024). "Furthermore, we examined the correlation between FGFR3 expression and tumor hallmark pathways in malignant cells." (PMID 37283287, 2023). "Finally, the FGFR3 c.742C>T mutation was found in only 7% of primary tumor specimens and 27% of metastatic sites." (PMID 38098507, 2023). "For instance, those patients with advanced or metastatic BC harboring FGFR3 mutations in their primary tumor are already being treated with the Food and Drug Administration (FDA)-approved drug Erdafitinib® (NCT05316155), a fibroblast growth factor receptor (FGFR) kinase inhibitor." (PMID 38098507, 2023). "Moreover, a strong association of FGFR3 mutation with low tumor grade and stage mutation has also been identified with high frequency in urothelial papilloma, a proposed precursor lesion for low-grade papillary urothelial cancer." (PMID 37048074, 2023). "FGFR3 overexpression was only associated with lower pT stage and tumor grade." (PMID 37493315, 2023). "Low-grade tumours ordinarily harbour relatively few genomic aberrations (often activating point mutations in oncogenes such as FGFR3, PIK3CA and RAS), typically exhibit luminal expression subtypes, and can be subdivided into two groups on the basis of CNVs (GS1 and GS2)." (PMID 35655252, 2022). "Thus, our observation that 9.5% of high-grade MIBC sampled from the primary tumor had FGFR3 mutations is reasonable based on the published literature." (PMID 35384983, 2022). "This was the first study to systematically investigate the unique transcriptomic profile determined by FGFR3 alterations, and the FGFR3 alteration-related transcriptomic characterization is implicated with biological activities, molecular features, and tumor immune infiltration of BC." (PMID 35958598, 2022). "The mutation frequency of FGFR3 was lower in the high-stromal group than that in the low-stromal group, suggesting that the smaller the mutation frequency of FGFR3, there may be more tumor stromal cells, thus making the tumor more prone to metastasis." (PMID 35991125, 2022).
tumor (continued). "Additionally, the low-risk BC patients with altered FGFR3 exhibited the highest tumor purity and the most activated T cells, which were associated with better treatment responses of immunotherapies." (PMID 36033441, 2022). "Because somatic mutation of TERT promoter and FGFR3, which were identified in the normal urothelium, have been reported as frequent mutations in tumor tissues by The Cancer Genome Atlas (TCGA), these mutations were thought to be potential drivers in the tumor formation of LG or HG NMIBC." (PMID 36198773, 2022). "As FGFR3 expression (activating mutations and/or copy number amplifications) is associated with low-grade tumours, FOXM1 regulon activity could be driving the transition from low- to high-grade NMIBC." (PMID 35655252, 2022). "Notably, the low-risk tumor groups have significantly lower rates of FGFR3 mutation while the overall mutation rates of RB1 appeared to be higher in the high-risk subgroup." (PMID 34490263, 2021). "Furthermore, elevated levels of FGFR1 and FGFR3 associated with tumor progression and drug resistance, also correlated with expression of c-MYC, another protein responsible for tumor angiogenesis." (PMID 34830951, 2021). "FGFR3 mutations commonly occur in the extracellular (R248C, S249C) and TM (G370C, Y373C) domains of the receptor, which are found to have the ability to stimulate proliferation in cell lines and lead to the transformation of fibroblasts into tumour cells." (PMID 33655556, 2021). "Notably, FGFR3 wild-type tumors harbored a high rate of SWI/SNF genetic tumor alterations and were associated with a higher level of tumor infiltrated lymphocytes (TILs)." (PMID 34503152, 2021). "Wild-type FGFR3 was associated with chemosensitive tumours (p = 0.055)." (PMID 34934968, 2021). "Pure LNUC is a prime example of a luminal, FGFR3-mutated, mostly PD-L1-negative tumor." (PMID 32213857, 2020). "The FGFR3 S249C mutation was mainly detected in ≤ pT1 tumor in pre-TURBT group 1." (PMID 32509577, 2020). "Finally, they selected three of these markers (the genes HS3ST2, SLIT2 and SEPTIN9) for combination with the FGFR3 mutations in a logistic regression model, obtaining a sensitivity of 94.5% (96% in high-grade tumours) and a specificity of 75.9%." (PMID 32664878, 2020). "In this study, FGFR3 expression was associated with tumor differentiation (p = 0.043 and p < 0.05), lymph node metastasis (p = 0.078 and p < 0.1), and race (p = 0.033 and p < 0.05), suggesting that FGFR3 may have an influence on the tumor development." (PMID 33381388, 2020). "The study shows that FGFR3 mutations may influence tumorigenesis by regulating an acute inflammatory response which via the immune cells destroys the tumor cells." (PMID 32397531, 2020).
tumor (continued). "Significant was also the correlation between the FGFR3 mutation and a low tumor grade." (PMID 32397531, 2020). "Therefore we used FGFR3 expression as surrogate of mutation, as most mutant tumours also have FGFR3 upregulation." (PMID 30952872, 2019). "Based on these, we developed an ultra-sensitive, urine-based assay called Uromonitor®, capable of detecting trace amounts of TERT promoter (c.1-124C > T and c.1-146C > T) and FGFR3 (p.R248C and p.S249C) hotspot mutations, in tumor cells exfoliated to urine samples." (PMID 31921291, 2019). "While this suggests that FGFR3 may be functionally associated with tumor invasion, whether FGFR3 signaling is driving GBM invasion remains to be shown." (PMID 31337028, 2019). "Similarly, FGFR3 mutation in combination with a 3-plex methylation assay was found to have a sensitivity of 79% and a specificity of 77% in detection of a tumor recurrence." (PMID 29931526, 2018). "Although involvement of FGF signalling has been reported in inflammatory diseases and in the tumour microenvironment 44, the mechanisms that underlie early suppression of the inflammatory response by S249C‐mutated FGFR3 are currently unknown." (PMID 30043421, 2018). "In summary, our study showed that the increased tumour progression could be initiated by the effects of FGFR3 mutations in regulating an acute inflammatory response, and that immune cells are perturbed in the tumour as a consequence." (PMID 30043421, 2018). "Importantly, moderate-to-strong FGFR3 immunostaining was significantly associated with shorter overall patient survival (p < 0.05, log-rank test) and shorter time to tumor recurrence (p < 0.01, log-rank test)." (PMID 28468611, 2017). "Furthermore, it is also possible that factors other than anti-tumour immune responses contribute to increased survival rates in tumours with FGFR3 mutations in MIBC." (PMID 29050337, 2017). "Eight FGFR3-mutation-carrying RPC tumours included two with A248C, 4 S249C, 1 G372C, and 1 T375C." (PMID 27029078, 2016). "Tumor growth in the PDX with an FGFR3 mutation was inhibited by the FGFR3 inhibitor." (PMID 26041878, 2015). "This patient case highlights that, in addition to patients harbouring FGFR3 hotspot mutations or fusions in their tumour, there is potential for additional UC patients with high expression of FGFR pathway components such as FGFR, ligand and FRS2 to gain benefit from FGFR inhibitor therapy." (PMID 26497743, 2015). "Tumours with FGFR3 mutations showed more MTUS1 expression loss than wild type tumours." (PMID 24650297, 2014). "Therefore, for tumors of epithelial origin, loss of FGFR3 was found in higher grade tumor while activating mutations of FGFR3 were found in benign or low grade tumor with good prognosis." (PMID 25469175, 2014).
tumor (continued). "Alternatively, after additional mutations have occurred in the developing tumor, decoupling FGFR3 from its canonical inhibitory pathway (STATs), FGFR3 signal might be redirected to other intracellular factors, promoting tumor progression." (PMID 23902722, 2013). "Importantly, frequent loss of heterozygosity of the chromosomal region carrying FGFR3 gene (the 4p16.3 locus) has been characterized, suggesting that this region carries a tumor suppressor gene." (PMID 23902722, 2013). "In addition, PCR analysis on isolated tumor tissue indicated the tumor carried the same FGFR3 mutation as that of the DNA isolated from urine, consistent with the tumor being the origin of the mutant DNA." (PMID 22873290, 2012). "The frequency of FGFR3 mutation was even lower in pT1G3 tumours (20.8%) and pT2-4 tumours (11.8%)." (PMID 23272046, 2012). "Most of the deregulated genes in the FGFR3-mutated tumor pathway were found in this group." (PMID 22724020, 2012). "However, for HC2a/HC3a tumors the frequency of CDKN2A deletions was drastically increased, suggesting that acquisition of CDKN2A deletions occurs later during tumor progression than for example FGFR3 mutations and 9q deletions." (PMID 22685613, 2012). "We also highlighted cell-type-dependent phenotypic and signalling consequences of specific FGFR3 mutations which may explain the differences in the relative frequencies between tumour types." (PMID 22899908, 2012). "These phenotypes are compatible with the hypothesis that FGFR3 mutation contributes early in the process of tumour development." (PMID 22899908, 2012). "Detection of FGFR3 mutations in urine could also be employed for general population screening aimed at early detection of primary tumours." (PMID 22899908, 2012). "For the follow-up of young patients presenting with an FGFR3 mutant NMI tumor, FGFR3 mutation analysis could be a feasible alternative for recurrence detection." (PMID 20187926, 2010). "In Patient 1, however, tumours 2–4 had the Y375C mutation, while tumour 1 was WT FGFR3." (PMID 17579624, 2007). "On the contrary, FGFR3 mutations are associated with low-grade tumours and a favourable prognosis." (PMID 17088904, 2006). "Moreover, contemporary investigations have demonstrated that novel structural changes in FGFR2 and FGFR3 are frequently linked to an aggressive tumor biology and specific gene expression signatures, thus validating their function as powerful, clinically actionable drivers." (PMID 41567627, 2025). "Similarly, using erdafitinib to target FGFR3 mutations, activation of other pathways may allow tumor cells to continue growing under FGFR3 inhibition." (PMID 39911393, 2025). "When a highly antigenic tumor is entirely composed of cells harboring an activating FGFR3 mutation, anti-FGFR3 therapy may be necessary to minimize tumor burden as ICI shifts the balance in the tumor-CTL interactions towards tumor cell lysis and away from CTL exhaustion." (PMID 38515743, 2024). "However, whether this finding from bulk RNA-seq is due to an expansion of luminal cells or whether FGFR3 mutations drive a luminal expression pattern across all tumor cells remains unresolved." (PMID 38226620, 2024).